BDNF-AS (BDNF antisense RNA)
Synonyms: BT2A; BT2B; BT2C; BT2D; NCRNA00049; BDNF-AS1; BDNFAS; ANTI-BDNF; BDNFOS
Gene: Long non-coding RNA gene on chromosome 11 (27,506,808 to 27,698,231, forward strand). Ensembl gene ENSG00000245573.
Diseases named in the same sentence as BDNF-AS in open-access papers:
BDNF-AS is named in the same sentence as 2 diseases in open-access papers, as found by Europe PMC text mining. Sharing a sentence is not in itself a finding about the gene and the disease.
BDNF-AS shares sentences with these, for which no sentence is quoted: infection (2 papers); lumbar disc degeneration (1).